HIF1A (hypoxia inducible factor 1 subunit alpha)
Diseases named in the same sentence as HIF1A in open-access papers (continued):
Sharing a sentence is not in itself a finding about the gene and the disease.
keloid (continued). "Furthermore, we first explored the function of the HIF-1α/HOXC6 axis via the ERK/MAPK pathway in KFs, providing candidate novel therapeutic targets for keloids." (PMID 35547861, 2022). "Although Hif1α levels in burn skin were not on par with keloid tissue, expression appeared to be elevated (0.63 vs. 0.28, P = 0.20)." (PMID 32750036, 2020). "Although the prominence of both hypoxia and the subsequent activation of HIF-1α in the tumor EMT process are known, their functions in regulating keloid pathological processes remain unclear." (PMID 25777304, 2015). "A statistically significant (P < .05) differential expression and a fold change of more than 2 were determined between keloid margin and internal control biopsy samples for 10 genes, including ACAN, ASPN, C5orf13, HIF1A, IGFBP7, INHBA, LGALS1, PTN, SERPINH1, and TNFAIP6." (PMID 20418938, 2010). "First, we did not compare VEGF, CD31, and HIF-1α expression between recurred and no recurred keloid patient whose radiated skin sample could not be collected." (PMID 36316928, 2022). "However, our study focused only on HBOT's effect on keloid tissue; thus, it did not clarify the mechanism of this process or the role of HIF-1α." (PMID 30024539, 2018). "In conclusion, our study demonstrates that HIF-1α upregulates vimentin and fibronectin expression and downregulates E-cadherin and ZO-1 expression in keloid keratinocytes under hypoxic conditions, which promotes the EMT process and enhances the invasive capacity of the keloid keratinocytes." (PMID 25777304, 2015). "Notably, this HIF-1α EMT signaling was inhibited and reversed by siRNA targeting HIF-1α, suggesting that HIF-1α may be the crucial EMT initiator and mediator in the hypoxia-induced EMT process in keloid scars." (PMID 25777304, 2015). "However, the role of HIF-1α in keloid formation and growth is still not clearly understood." (PMID 25777304, 2015).
Myocardial fibrosis (26 papers, 2014 to 2026). "Zhao discovered that low-intensity pulsed ultrasound treatment can reverse myocardial fibrosis caused by prolonged hypoxia via the TRAAK-mediated HIF-1α/DNMT3a signaling pathway." (PMID 39091919, 2024). "However, whether HIF-1α is involved in myocardial fibrosis, and the associations between HIF-1α, transforming growth factor-β1 (TGF-β1) and matrix metalloproteinase-9 (MMP-9) remain unknown." (PMID 25371714, 2014). "Cardiomyocyte-specific abolishment of Hif-1a blunted the disease phenotype, as evidenced by decreased left ventricular wall thickness, reduced myocardial fibrosis, disordered SRX/DRX state and ROS production." (PMID 39820339, 2025). "The contribution of the H2S/CBS pathway to high-salt–induced myocardial fibrosis (MF) was explored, with a focus on the mechanistic involvement of hypoxia-inducible factor-1α (HIF-1α)." (PMID 40642013, 2025). "The release profile was coped with the request for HIF‐1α stabilization in short‐term cardiomyocyte apoptosis and long‐term myocardial fibrosis after MI." (PMID 39308185, 2024). "In conclusion, our studies suggest that MYBPC3 deficiency in cardiac fibroblasts can promote their trans-differentiation into myofibroblasts via NF-κB/TGF-β1/HIF-1α/aerobic glycolysis signal cascade, contributing to premature myocardial fibrosis." (PMID 36357371, 2022). "Both the TGF-β/Smad and Hif-1α pathways have been demonstrated to be key signaling pathways in Ang II-induced myocardial fibrosis." (PMID 31700166, 2020). "We then analysed the expression of fibrosis-related proteins (MMP2, MMP9 and collagen I) to determine the roles of TGF-β1/Smad and HIF-1α pathways in myocardial fibrosis." (PMID 25823960, 2015). "In this study, we demonstrated that Hif-1α pathway also participated in Ang II-mediated myocardial fibrosis after MI." (PMID 25823960, 2015). "In this study, we simultaneously explored the effects of TGF-β and Hif-1α in Ang II-induced myocardial fibrosis and revealed that Hif-1α was another factor in the process." (PMID 25823960, 2015). "In summary, we confirmed that both TGF-β and Hif-1α played important roles in Ang II-mediated myocardial fibrosis after MI." (PMID 25823960, 2015). "The expression of HIF-1α and the extent of myocardial fibrosis was positively correlated, which implies that HIF-1α can facilitate the expression level of TGF-β1 and thus induce atrial fibrosis." (PMID 25371714, 2014). "For instance, stemness-related genes such as Cd34 and Hif1a, as well as pathways involved in oxidative phosphorylation and glutathione metabolism, should be closely monitored in future efforts to prevent post-MI myocardial fibrosis." (PMID 40595870, 2025). "Additionally, myocardial fibrosis markers were significantly reduced, accompanied by a decrease in the myocardial mRNA and protein expression of glycolytic proteins, including HIF-1α, PFKFB3, GLUT1, and LDHA." (PMID 40944191, 2025). "In this study, though we demonstrated the synergetic roles of TGF-β1 and HIF-1α in Ang II-mediated myocardial fibrosis after MI, we failed to reveal the underlying mechanisms of Ang II-induced synergistic effects of the TGF-β1 and HIF-1α signalling pathways." (PMID 25823960, 2015). "The results suggest that the TGF-β and Hif-1α pathways may play synergetic roles in myocardial fibrosis, and the cardiac protection by valsartan after MI was through inhibiting both TGF-β and Hif-1α." (PMID 25823960, 2015). "Furthermore, HIF-1α can be involved in myocardial fibrosis formation by regulating the MMP-9 expression level." (PMID 25371714, 2014). "Studies have found that as an upstream pathway in multiple pathophysiological processes of Hif1α, RhoA/ROCK signaling pathway mediates Hif1α to promote myocardial fibrosis and apoptosis, and this process is negatively regulated by Notch3142." (PMID 40520009, 2025).
Myocardial fibrosis (continued). "It is found that abnormal expression of HIF1A in the sympathetic nervous system affects myocardial collagen deposition, ECM formation, and myocardial fibrosis in diabetic cardiomyopathy." (PMID 38355637, 2024). "Administration of valsartan attenuated myocardial fibrosis through inhibiting both TGF-β and Hif-1α pathways." (PMID 25823960, 2015). "By inhibiting the expression of HIF-1α, the expression levels of TGF-β1 and MMP-9 decreased accordingly, and the extent of myocardial fibrosis was also reduced." (PMID 25371714, 2014). "HIF1-α was expressed in both DCM and ICM hearts (0.95 ± 0.16 versus 0.82 ± 0.07 a.u.), independently from the magnitude and distribution of myocardial fibrosis." (PMID 24444256, 2014). "HIF-1α can increase the expression of matrix metalloproteinases (MMPs) and transforming growth factor (TGF)-β in AF through promoting atrial fibrosis, and inhibiting the expression of HIF-1α can decrease the levels of TGF-β and MMP-9 accompanied by the less myocardial fibrosis in rabbit models." (PMID 38274270, 2023). "It was found that pretreatment with the prolyl hydroxylase inhibitor dimethyloxalylglycine enhanced a CH-induced increase in the HIF-1α level in myocardial tissue, and attenuated RV hypertrophy and myocardial fibrosis, consequently, HIF-1α did not trigger RV hypertrophy in CH." (PMID 37183617, 2022). "In addition, whether interaction or synergetic roles between Hif-1α and TGF-β pathways existed in myocardial fibrosis after MI was unclear." (PMID 25823960, 2015). "Although studies have shown that the increase in HIF-1α gene expression in the myocardium may be involved in its structural changes, including atrial fibrosis, no study has been conducted for the elevated AngII-induced myocardial fibrosis." (PMID 25371714, 2014).
cerebral infarction (25 papers, 2012 to 2025). An ischemic condition of the brain, producing a persistent focal neurological deficit in the area of distribution of the cerebral arteries. "The results indicated that JCT could treat ICS by reducing the symptoms of cerebral infarction and enhancing neuroprotective effects, and its action mechanisms were associated with the activation of the HIF-1α/EPO/VEGFA pathway." (PMID 36269045, 2022). "Through bioinformatics analysis, we identified key targets associated with cellular senescence and circadian rhythm in cerebral infarction, specifically CREBBP, FOS, CDK4, MMP9, PTEN, and HIF1A." (PMID 40629591, 2025). "NBO up-regulates the level of HIF-1α, increases cerebral blood flow and reduces the volume of cerebral infarction." (PMID 39139771, 2024). "The inhibition of HIF-1a and its downstream genes can reduce HT in cerebral infarction and improve neurological dysfunction after focal cerebral ischemia." (PMID 35757529, 2022). "In a study of 40 patients with acute ischemic stroke, elevated serum HIF-1α levels were closely related to cerebral infarction size." (PMID 36570456, 2022). "The experiments showed that HCC can improve the neurological deficit score, decrease the volume of cerebral infarction and up-regulate the expression of HIF-1α/VEGF and VEGFR protein and mRNA (p < 0.05)." (PMID 34248611, 2021). "MSC with HIF-1α hyperexpression promoted reduction of brain infarct volume, improved neurobehavioral outcome and, additionally, inhibition of proinflammatory cytokine secretion while promotion of neurotrophin release." (PMID 34572364, 2021). "Brain infarct volume, blood-brain barrier permeability, tight junction protein expression, and hypoxia inducible factor-1α (HIF-1α) mRNA level were examined after treatment." (PMID 28697748, 2017). "Transplantation of the overexpressed Hif-1α of BMSCs into the MCAO rats reduced brain infarct volume and improved neurobehavioral outcome; besides, it inhibited pro-inflammatory cytokines generation while promoted neurotrophin secretion." (PMID 28424584, 2017). "Transplantation of the overexpressed Hif-1α of BMSCs into the MCAO rat significantly reduced brain infarct volume and improved neurobehavioral outcome." (PMID 28424584, 2017). "Results showed that BMSCs significantly reduced brain infarct volume, and Hif-1α overexpression strengthened this reduction (P < 0.05)." (PMID 28424584, 2017). "Taken together, these findings suggest that the HIF-1α/TIM-3 axis may be closely involved in neurological function as well as cerebral infarct volume and pathophysiological inflammatory events." (PMID 25790768, 2015). "At 4 h after the beginning of the experiment, HIF-1α and EPO in the HBO group increased, and the volume of cerebral infarction decreased." (PMID 39139771, 2024). "2ME2 and IL-4+2ME2 groups had decreased NDS, cerebral infarction volume, brain water content, apoptosis rate and MDA, ROS, HIF-1α, BNIP3, LC3-II and Beclin-1 levels, but increased SOD level compared with those of IL-4 group (P<0.05)." (PMID 36910409, 2022). "Compared with IR group, NDS, cerebral infarction volume, brain water content, apoptosis rate, and MDA and ROS levels decreased, while SOD, HIF-1α, BNIP3, LC3-II and Beclin-1 levels increased in IL-4 group (P<0.05)." (PMID 36910409, 2022). "Overexpressed Smurf2 or downregulated YY1, HIF1α, or DDIT4 reduced the volume of cerebral infarction and apoptosis in MCAO mice, while enhancing cell viability and reducing apoptosis and lactate dehydrogenase leakage in OGD-treated neurons." (PMID 33722608, 2021). "HIF-1α contributes to MSC survival and efficacy of MSC application for treatment (by cell transplantation) cerebral infarction in the animal model of cerebral artery occlusion." (PMID 34572364, 2021). "Endothelial-specific HIF-1α knockout diabetic mice showed reduced BBB disruption and decreased brain infarction." (PMID 34966392, 2021).
cerebral infarction (continued). "One study reported that the expression of miRNA-26a in cells is up-regulated after cerebral infarction in rats, which can activate PI3K/AKT, and the MAPK/ERK pathway up-regulates the expression of HIF-1a, which mediates the transcriptional activity of VEGF and promotes rat angiogenesis." (PMID 34046349, 2021). "l-borneol can also inhibit neuronal apoptosis and enhance the stability of neovascularization by inhibiting the levels of ACE, MMP9, HIF1α, TGF-β1 and Tie2, thereby improving the neurological deficit in ischemic rats, reducing the rate of cerebral infarction, and exerting neuroprotective effects." (PMID 33746762, 2021).
epilepsy (25 papers, 2015 to 2025). A brain disorder characterized by episodes of abnormally increased neuronal discharge resulting in transient episodes of sensory or motor neurological dysfunction, or psychic dysfunction. "HIF-1α not only affects ischemia-induced hippocampal neuronal loss by regulating lactate metabolism but is also closely associated with epilepsy-related hippocampal neuronal death and oxidative stress." (PMID 39876842, 2024). "According to the multivariate regression analysis, only four variables remained significantly associated with survival: age, extent of surgery, epilepsy, and HIF-1α expression." (PMID 38927417, 2024). "It is known that STAT5B is a negative regulator of xCT expression, and HIF-1α is mediated by connexin 43 (Cx43), whose augmentation is linked to glioma-related epilepsy." (PMID 36295510, 2022). "That is, The accumulation of HIF-1α in VPA-resistant epilepsy caused activation of microglia and aggravated the release of proinflammatory mediators." (PMID 34497517, 2021). "Evidence suggest that overexpression of hypoxia-inducible factor-1α (HIF-1α) is linked to multidrug resistance of epilepsy." (PMID 27554040, 2016). "This might be linked to up-regulation of HIF-1α in the patients’ brain tissue and provide a promising therapeutic target for refractory epilepsy." (PMID 27554040, 2016). "This raises the possibility that abnormally expressed miRNAs which contribute to the pathogenesis of epilepsy and enhanced expression of HIF-1α could be, at least in part, caused by loss of expression of some regulatory miRNAs." (PMID 27554040, 2016). "However, the interaction between HIF-1α and HO-1, along with their neurotoxic mechanisms associated with hippocampal neuronal ferroptosis in epilepsy, remains unclear." (PMID 37876811, 2023). "However, the underlying mechanism of HIF-1α deregulation in epilepsy remains poorly understood." (PMID 27554040, 2016). "From both studies, it emerges that miR-153, through the regulation of HIF-1α expression, contributes to the pathogenesis of drug-resistant epilepsy." (PMID 38525737, 2024). "Nowadays, it is known that HIF-1α actively contributes to the pathogenesis of pharmacoresistant epilepsy." (PMID 38525737, 2024). "This research investigates the role of hypoxia-inducible factor (HIF)-1α/heme oxygenase (HO)-1 in hippocampal neuron ferroptosis during epilepsy." (PMID 37876811, 2023). "To verify that HIF-1α/HO-1 pathway is activated in epilepsy, we performed RT-qPCR and western blot assays to detect hippocampal tissues of PTZ and CON mice at transcriptional and translational levels." (PMID 37876811, 2023). "PTZ-kindled mice model confirms increased ferroptotic markers, oxidative stress, HIF-1α, and HO-1 in epilepsy." (PMID 37876811, 2023). "First of all, the study predominantly establishes correlations between the HIF-1α/HO-1 pathway activation, ferroptosis markers, and epilepsy." (PMID 37876811, 2023). "Study implicates HIF-1α/HO-1 potentially regulates hippocampal neuronal ferroptosis, iron metabolism, and oxidative stress, thereby promoting the propagation of epilepsy." (PMID 37876811, 2023). "This study combines metabolomics with human disease public databases to uncover the potential role of the HIF-1α/HO-1 pathway in hippocampal neuronal ferroptosis during epilepsy." (PMID 37876811, 2023). "We showed that downregulation of miR-221-3p expression in VPA-resistant epilepsy led to accumulation of its negative regulatory target gene: HIF-1α." (PMID 34497517, 2021). "Above results evidence that upregulation of HIF-1α expression in VPA-resistant epilepsy leads to increased expression of IL-1β and TNF-α." (PMID 34497517, 2021). "This is the first study to demonstrate the significance of miR-221-3p/HIF-1α in VPA-resistant epilepsy." (PMID 34497517, 2021). "The role of HIF-1α in the mechanism of VPA-resistant epilepsy is still unclear or even controversial." (PMID 34497517, 2021).